ALB (albumin)
Diseases named in the same sentence as ALB in open-access papers (continued):
Sharing a sentence is not in itself a finding about the gene and the disease.
hyperlipidemia (164 papers, 2008 to 2026). "LASSO-logistic regression analysis identified seven predictors associated with PSS: C-reactive protein, albumin, creatine kinase, fasting blood glucose, hyperlipidemia, sleep disorders, and manual muscle testing (MMT) score at admission." (PMID 41432712, 2026). "Five turtles with moderate to severe lipemia were excluded from analysis as lipaemic index demonstrated a significant association with total protein (P < 0.001), albumin (P = 0.002), triglyceride (P < 0.001) and calcium (P < 0.001)." (PMID 38765884, 2024). "In this study, presence of a history of hyperlipidemia, regular exercise, higher albumin level, and higher HDL level were related to a lower risk of cognitive impairment." (PMID 36864383, 2023). "Male gender, a history of hyperlipidemia, exercise, a high albumin level, and a high HDL level seemed to be associated with a lower risk of cognitive impairment amongst older adults." (PMID 36864383, 2023). "Alternatively, being a male, having a history of hyperlipidemia, regular exercise, and higher albumin and HDL levels were related to a lower risk of cognitive impairment." (PMID 36864383, 2023). "Male gender, hyperlipidemia, exercise, albumin level, and HDL level were related to a lower risk of cognitive impairment." (PMID 36864383, 2023). "Hyperlipidemia can cause renal tubular injury when combined with proteinuria by the mechanism that albumin can act as a carrier of fatty acids and promote the deposition of fatty acids in kidney." (PMID 35873008, 2022). "In this study, we established a protein-overload nephropathy CKD mouse model by bovine serum albumin (BSA) injection to investigate whether hyperlipidemia could accelerate CKD progression and the underlying mechanisms." (PMID 36045744, 2022). "We demonstrated that deletion of apoE per se was associated with hyperlipidemia via elevations in plasma levels of both cholesterol and triglycerides; however, little consequent effect on urinary albumin excretion, plasma cystatin C levels or glomerular matrix accumulation were observed." (PMID 32581831, 2020). "In summary, our study developed a practical predictive nomogram that identifies seven variables associated with PSS, including CRP, ALB, CK, FBG, hyperlipidemia, sleep disorders, and MMT score, to assess the risk of PSS." (PMID 41432712, 2026). "The albumin levels and the prevalence of hyperlipidemia were significantly lower in the PT group than in the HC group (both p = 0.002)." (PMID 40612804, 2025). "The levels of total protein and albumin in the hyperlipidemia group were slightly higher but insignificantly different from the treated or control groups." (PMID 41144456, 2025). "All covariates linked to the risk of 30-day ACM were identified, including age, SBP, albumin, BUN, INR, LDH, blood lipases, phosphate, TbIL, AKI, DM, hyperlipidemia, norepinephrine use, and statins use." (PMID 40301794, 2025). "NS is a group of syndromes caused by various kidney diseases, characterized primarily by significant proteinuria (greater than 3.5 g/day), hypoproteinemia (serum albumin <30 g/L), edema, and hyperlipidemia." (PMID 39944614, 2025). "Compared to the hyperlipidemia group, garlic scapes showed an increase in serum albumin at various dose levels." (PMID 39479679, 2024). "In the fourth and eighth weeks, albumin decreased in the hyperlipidemia group compared to other groups." (PMID 39479679, 2024). "Laboratory findings showed nephrotic-range proteinuria (24 g/24 h) with microscopic hematuria (RBCs 4-5 per hpf), low serum albumin (2 g/dL) and hyperlipidemia (total cholesterol 338 mg/dL, triglycerides 156 mg/dL, low high-density lipoprotein 187 mg/dL)." (PMID 37374047, 2023). "Hyperlipidemia resulting from the compensatory hepatic synthesis of lipoproteins in response to urinary albumin leak can aggravate glomerular sclerosis and interstitial fibrosis." (PMID 35328466, 2022).
hyperlipidemia (continued). "In the validation cohort, we also made a model that included age, history of hyperlipidemia, albumin level, and MLR." (PMID 36247122, 2022). "In the nephrotic group, serum albumin level was significantly lower, and the rate of hyperlipidemia was markedly higher than in the sub nephrotic group, as expected." (PMID 35786180, 2022). "Age (p = 0.031), history of hyperlipidemia (p = 0.014), and albumin level (p = 0.012) also had a meaningful relationship with poor prognosis." (PMID 36247122, 2022). "Sex, hyperlipidemia, disease severity, hospital stay before surgery, preoperative insertion of the central venous catheter, Caprini score, albumin, and d-dimer levels were found to be significant factors in the univariate analysis." (PMID 36776649, 2021). "GATE administration significantly ameliorated symptoms of proteinuria and hyperlipidemia in NS mice, as evidenced by reduced excretion of urine protein and albumin, and decreased plasma levels of total cholesterol and triglyceride." (PMID 32765640, 2020). "Hyperlipidemia has been shown to result in glomerular Apo-B accumulation, glomerular hypertrophy, increasing urine albumin, elevating transforming growth factor (TGF-β) levels, and continuous renal injury." (PMID 32460759, 2020). "Clinically, in addition to the low level of albumin, the patients almost always have hyperlipidemia, but they usually also have mild oedema, reduced blood pressure and fatigue." (PMID 31057599, 2019). "Protein damage can also be induced by S-thiolation, as recently shown for human serum albumin from hyperlipidemia patients, which carries Hcy and Cys bound via a disulfide bond to albumin Cys residues normally engaged in intrachain disulfide bonds." (PMID 30345292, 2018). "Persistent severe albuminuria reduces the serum albumin level and leads to a compensatory increase of albumin synthesis in the liver, but lipoprotein synthesis is also increased simultaneously and hyperlipidemia occurs." (PMID 29808114, 2018). "Self-rated health, treatment of any disease, and presence of diseases such as respiratory disease and hyperlipidemia were intermediate factors in the relation of serum albumin with economic status in the low-income group." (PMID 27276092, 2016). "The eXtreme Gradient Boosting (XGBoost) model, constructed based on six variables: body mass index (BMI), history of hyperlipidemia, homocysteine (Hcy), glycated albumin (GA), small dense low-density lipoprotein cholesterol (sdLDL-C) and UHR, demonstrated the best performance." (PMID 42305866, 2026). "Hyperlipidemia impacts global mortality, and the neutrophil-percentage-to-albumin ratio (NPAR) is a novel inflammatory marker, but its association with mortality in hyperlipidemic adults is unknown." (PMID 41995492, 2026). "Our goal was to optimize albumin-based nanoparticles loaded with Repaglinide for parenteral delivery and conduct in silico and in vivo studies to explore the efficacy of Repaglinide for the management of hyperlipidemia along with its anti-diabetic effect." (PMID 40143014, 2025). "However, RBC, hemoglobin, HCT, MCH, MCHC, ALT, albumin, protein, BMI, hyperlipidemia, and smoking were negatively correlated with a 3-month unfavorable outcome (p < 0.05)." (PMID 40248032, 2025). "Laboratorial findings were remarkable for nephrotic-range proteinuria (9.7 g/24 h) without microscopic hematuria, eosinophiluria or aseptic pyuria; low serum albumin (1.6 g/dL); and hyperlipidemia (total cholesterol 459 mg/dL, triglycerides 282 mg/dL, low high-density lipoprotein 322 mg/dL)." (PMID 37374047, 2023). "In the same study, lipemia, icterus, autoagglutination, hemolysis and reticulocyte count did not affect Hct values, however, to the authors' knowledge, the influence of albumin on Hct measurement in veterinary medicine is unknown." (PMID 36090165, 2022).
hyperlipidemia (continued). "The results showed that the negative association between HbA1c and albumin was relatively stable in people of different genders or BMI, or people with or without hyperlipidemia or hyperuricemia." (PMID 34055818, 2021). "In addition, a decrease in serum ALB levels can increase the concentration of free lysophosphatidylcholine, stimulate the synthesis of lipids and coagulation factors, and increase blood viscosity, resulting in hyperlipidemia and a hypercoagulable state." (PMID 37658287, 2023). "Therefore, when factors that affect conductivity (sodium, chloride, albumin, white blood cells, lipemia, anticoagulant and intravenous fluid therapy) become abnormal, the Hct measured may be inaccurate." (PMID 36090165, 2022). "The relation between serum albumin level and low income became statistically insignificant when “body mass index”, “consumption of meat or fish”, “self-rated health”, “presence of medical conditions”, “hyperlipidemia”, or “respiratory disease “was included in the model." (PMID 27276092, 2016). "The results identify CRP, ALB, CK, FBG, hyperlipidemia, sleep disorders, and MMT score as key predictors for PSS." (PMID 41432712, 2026). "This patient had a CK level of 340 U/L, albumin level of 46 g/L, FBG of 6.0 mmol/L, CRP level of 9 mg/L, presence of sleep disorders, a MMT grade of 0–3, and hyperlipidemia." (PMID 41432712, 2026). "This group also had fewer males and smokers, a lower incidence of hyperlipidemia, reduced STEMI occurrences, fewer patients with Killip class ≥ II, and lower levels of LVEF, BMI, DBP, hemoglobin, albumin, triglycerides, ApoA1, and eGFR (P < 0.05)." (PMID 38812817, 2024). "There were no significant between-group differences in other serum parameters (UA, HCY, FBG, ALT, AST, Cre, PAB, ALB, GLB, TP, ALP, γ-GT, T-BIL; P > 0.05), indicating the comparability between the hyperlipidemia and healthy groups." (PMID 38812752, 2024). "Laboratory tests showed creatinine (Cr) of 2.23 mg/dL with a baseline of 1.5 mg/dL, albumin of 1.8, blood natriuretic peptide (BNP) of 667.88, and lipidemia." (PMID 34557371, 2021). "In the T2DM subgroup, medical history of HT or hyperlipidemia, and BNP level showed a gradually increasing trend, whereas medical history of family CVD, CAD, and MI and the levels of TC, DBIL, and ALB showed a gradually decreasing trend." (PMID 34675887, 2021). "Significant negative interferences for albumin (Alb) were determined in both lipemia types, but the interference in NULM spiked pools was not clinically significant." (PMID 38665874, 2024). "Laboratory findings showed nephrotic-range proteinuria (6.4 g/24 h) without microscopic hematuria, low serum albumin (2 g/dL) and hyperlipidemia (total cholesterol 400 mg/dL, triglycerides 265 mg/dL, low high-density lipoprotein 280 mg/dL)." (PMID 37374047, 2023). "the female patients had a longer duration of schizophrenia; higher levels of hyperlipidemia, total cholesterol, HDL-C, eGFR, and FABP3, and lower levels of uric acid, creatinine, albumin, hematocrit, hemoglobin, and high-sensitivity CRP, white blood cell count and were older than the male patients." (PMID 37255976, 2023). "Laboratory analysis showed that he had hyperlipidemia (total cholesterol 6.99 mmol/L, LDL-C 3.78 mmol/L, triglyceride [TG] 2.51 mmol/L), decreased serum albumin 26 g/L, as well as normal serum creatinine 68 μmol/L and estimated glomerular filtration rate 123.54 mL/min." (PMID 35119017, 2022). "We compared the demographic and clinic pathologic characteristics of patients in the two groups and found differences in race, insurance, CAD, hyperlipidemia, admission to the ICU, WBC, albumin, TBil, AST, BUN, glucose, bicarbonate, sodium, potassium, LOS, and in-hospital mortality." (PMID 35769519, 2022).
hyperlipidemia (continued). "In the younger participants (age, <65 years), the odds ratio (95% confidence interval [CI]) of low eGFR was 1.17 (1.02 to 1.34) for each 1 year older age, 6.28 (1.41 to 28.03) for urinary albumin creatinine ratio (ACR) over 17.9 mg/g and 9.43 (2.55 to 34.91) for hyperlipidemia." (PMID 19860890, 2009). "Additionally, those in the highest group exhibited increased FBG, SUA, waist circumference, TG, TC, LDL-C, Non-HDL-C, eGFR, albumin and higher rates of smoking, drinking and hyperlipidemia (p < 0.05)." (PMID 39866802, 2024). "Laboratory findings were remarkable for nephrotic-range proteinuria (18 g/24 h) without microscopic hematuria or eosinophiluria, low serum albumin (1.9 g/dL), hyperlipidemia (total cholesterol 467 mg/dL, triglycerides 342 mg/dL) and raised creatinine (5.8 mg/dL)." (PMID 37374047, 2023). "The systolic BP, DM duration, HbA1c level, and prevalence of hyperlipidemia and ARB/ACEi use tended to increase in patients with higher urinary albumin excretion, while estimated glomerular filtration rate tended to be lower in patients with increased albumin excretion." (PMID 37916147, 2023). "Low ALB levels act as a compensatory response by stimulating the synthesis of lipoproteins and procoagulative factors (such as factor V and VIII and FIB), resulting in hyperlipidemia and a hypercoagulable state, ultimately promoting atherosclerotic plaque formation and thrombosis." (PMID 37658287, 2023). "Other metabolic parameters such as fasting glycaemia as well as markers of general organ functions (total plasma proteins), including kidney (creatinine, urea) and liver (albumin) resulted unaltered (data not shown), suggesting that hyperlipidemia represents an early event in FRDA." (PMID 31974344, 2020). "According to Agarwal study, glucose and albumin are not affected by lipemia." (PMID 32104611, 2020).
Insulin resistance (156 papers, 2005 to 2026). Increased resistance towards insulin, that is, diminished effectiveness of insulin in reducing blood glucose levels. "The increase in ANGPTL8 synthesis was ascribed to albumin loss, a condition that leads to insulin resistance and heightened insulin requirements in individuals with T2D and albuminuria." (PMID 38790911, 2024). "Previous studies have demonstrated that increased serum ALB levels are related to several atherogenic risk factors including lipid profile, blood pressure, body mass index, and insulin resistance." (PMID 39345890, 2024). "The rise in ANGPTL8 production was attributed to losing albumin, which causes insulin resistance and increased need for insulin in people with T2D and albuminuria." (PMID 37762544, 2023). "In agreement with previous observations that steatosis is associated with insulin resistance and T2D risk, we report here that prevention of liver steatosis by albumin deficiency improved the regulation of blood glucose levels." (PMID 37432201, 2023). "Vitamin D at free form and vitamin D binding to albumin are defined as bioavailable vitamin D. Vitamin D deficiency is associated with atherogenic lipid profile and insulin resistance." (PMID 33728195, 2021). "Higher serum albumin in the setting of insulin resistance is thought to be the consequence of increased albumin production caused by insulin stimulation." (PMID 30786864, 2019). "Interventions aimed at optimizing serum Ca and albumin might not only help in reducing the risk of developing insulin resistance, which is prevalent in this demographic, but also in strengthening the skeletal system." (PMID 41019331, 2025). "Urinary albumin loss has been associated with insulin resistance, which in turn causes the production of hepatic hormones, that may act as mediators of the increased proliferation of B cells in T2DM." (PMID 39030467, 2024). "Insulin resistance is consistently associated with increased urinary albumin excretion." (PMID 37680883, 2023). "Additionally, more prospective studies are required to fully understand the associations between fructosamine, albumin, insulin resistance, and inflammation throughout pregnancy." (PMID 36235652, 2022). "Thus, loss of muscle mass and strength lead to exacerbated insulin resistance, which can increase profibrotic elements and vascular growth factors involved in damaging glomerular function and eventually end in albumin leakage." (PMID 32238873, 2020). "In addition, loss of albumin in urine has been implicated insulin resistance, which causes liver produced hormones as potential mediators of the increased β-cell proliferation in T2DM." (PMID 26739836, 2016). "This increase may be related to loss of albumin causing increased insulin resistance and higher demand for insulin in T2DM patients with albuminuria." (PMID 26739836, 2016). "In addition, insulin resistance indicators, such as fasting insulin and HbA1c, abdominal adiposity (waist circumference) and serum albumin/globulin ratio were negatively associated circulating irisin level." (PMID 24709991, 2014). "Furthermore, proteinuria (reflecting low serum albumin) is associated with retinol binding protein, a marker of insulin resistance recently identified as an independent risk factor of retinopathy." (PMID 23226496, 2012). "In addition, recently, serum albumin has been suggested to be associated with insulin resistance." (PMID 26739836, 2016). "After 18 months of CPAP therapy, OSA patients showed significant improvements in insulin resistance, lipid profiles (total cholesterol and VLDL), liver function markers (AST and albumin), and steatosis risk scores (Fatty Liver Index and OWLiver test)." (PMID 40867867, 2025). "Protective effects of NAC against insulin resistance and adipose tissue inflammation were shown in advanced glycated albumin (AGE-albumin) treated healthy rats." (PMID 41149623, 2025).